Y_RNA (Y RNA )
Gene: Miscellaneous RNA gene on chromosome 17 (75,145,670 to 75,145,762, forward strand). Ensembl gene ENSG00000252042.
Homologues: Orthologues: chimpanzee Y_RNA (100% identical). Paralogues in human: RNY1 (87% identical), Y_RNA (86% identical), Y_RNA (85% identical), Y_RNA (84% identical), Y_RNA (83% identical), Y_RNA (82% identical), RNY1P11 (81% identical), Y_RNA (81% identical), RNY1P12 (80% identical), Y_RNA (80% identical), RNY1P8 (78% identical), Y_RNA (78% identical), and 94 more.